FMR1 (fragile X messenger ribonucleoprotein 1)
Diseases named in the same sentence as FMR1 in open-access papers (continued):
Sharing a sentence is not in itself a finding about the gene and the disease.
fragile X syndrome (continued). "Fragile X syndrome is the most common inherited form of intellectual disability and is caused by the transcriptional silencing of the Fmr1 gene and the lack of fragile X messenger ribonucleoprotein (FMRP)." (PMID 40172581, 2025). "Moreover, studies in a fragile X syndrome mouse model suggest that metformin ameliorated the aberrant synaptic release and the Munc18-1 accumulation in Fmr1-KO neurons and inhibited the translation of synaptic proteins in presynapses." (PMID 39770443, 2024). "An understanding of the disorders began with the identification of (CGG)n trinucleotide repeats within the 5′ untranslated region (UTR) of FMR1 gene in Fragile X syndrome and (CAG)n trinucleotide repeats within the coding region of the androgen receptor (AR) gene in spinobulbar muscular atrophy." (PMID 38929088, 2024). "Diagnostic data for karyotypes, chromosomal microarrays, or FMR1 CGG-repeat expansion tests for the Fragile X syndrome, was not included in this study." (PMID 38539105, 2024). "Fragile X syndrome (FXS) is caused by the lack of fragile X messenger ribonucleoprotein (FMRP) that is encoded by the Fmr1 gene." (PMID 38374465, 2024). "A mouse model of Fragile X Syndrome with a KO of the Fmr1 gene not only resulted in anxiety and abnormal social behaviors but also increased GluA2 surface expression and reduced S880 phosphorylation of GluA2 in the hippocampus, the phosphorylation that is related to AMPAR endocytosis." (PMID 39056071, 2024). "Fragile X syndrome is caused by a reduction or complete absence of fragile X messenger ribonucleoprotein 1 (FMRP)." (PMID 39624684, 2024). "Silencing of the fragile X messenger ribonucleoprotein 1 (FMR1) gene and a consequent lack of FMR protein (FMRP) synthesis are associated with fragile X syndrome, one of the most common inherited intellectual disabilities." (PMID 38672417, 2024). "SNPs and small deletions in key FMR1 gene domains may result in fragile X syndrome (FXS)-like characteristics." (PMID 38646326, 2024). "Furthermore, to corroborate the therapeutic potential of buprenorphine on social behavior deficits, we performed an efficacy study using Fmr1-KO mice, a well-established animal model of fragile X syndrome." (PMID 39641273, 2024). "Mutant Fmr1 KO mice and rats display altered social interaction and social play behavior, social anxiety, defects in visual attention and auditory dysfunctions, cognitive deficits, repetitive behaviors, and hyperactivity mimicking fragile X syndrome in humans." (PMID 36834699, 2023). "This inactivates FMR1 expression and results in fragile X syndrome (FXS)." (PMID 36692473, 2023). "In those with the normal FMR1 gene, the number of CGG repeats lies between 5 and 44, while individuals carrying alleles with a repeat expansion greater than 200 develop fragile X syndrome (FXS), the most common form of intellectual disability and monogenic cause of autism spectrum disorder (ASD)." (PMID 37686279, 2023). "Fragile X syndrome (FXS) is a major neurodevelopmental disorder (NDD) caused by the absence of fragile X mental retardation protein (FMRP), coded by the FMR1 X-linked gene and involved in synaptic functionality." (PMID 37511156, 2023). "Fragile X syndrome (FXS) is the most common form of monogenic intellectual disability and autism, caused by the absence of the functional fragile X messenger ribonucleoprotein 1 (FMRP)." (PMID 36899894, 2023). "Fmr1 knockout (KO) mice are the best characterized model to study fragile X syndrome." (PMID 37547211, 2023).
fragile X syndrome (continued). "Concordantly, PACAP rescues hippocampal synaptic plasticity through stimulation of adenylate cyclase, and corrects abnormal metabotropic glutamate receptor-mediated long-term depression in the hippocampal neurons of Fragile X Mental Retardation 1 (Fmr1) knockout mice, a Fragile X Syndrome model." (PMID 37631246, 2023). "Furthermore, in Fragile X Syndrome, Fmr1 knockout mice presented primary ciliary deficits in the dentate gyrus of the hippocampus, also presenting lower cilia count and ciliary length." (PMID 37628781, 2023). "In particular, the absence of RA-RARα-regulated homeostatic plasticity mechanisms have been established in both Fmr1 knockout mice (a mouse model for fragile X syndrome [FXS]) and human neurons differentiated from FXS patient-derived induced pluripotent stem cells." (PMID 36515276, 2022). "Both white-eyed and red-eyed wild-type flies exhibit increased activity after the application of stimuli, while no changes can be observed in Fmr1 null allele flies, a model of fragile X syndrome." (PMID 36527001, 2022). "Fragile X-associated tremor/ataxia syndrome (FXTAS) and fragile X syndrome (FXS) are primary examples of fragile X-related disorders (FXDs) caused by abnormal expansion of CGG repeats above a certain threshold in the 5′-untranslated region of the fragile X mental retardation (FMR1) gene." (PMID 36110216, 2022). "Fragile X syndrome (FXS) is a neurodevelopmental disorder due to a mutation in the X-linked FMR1 human gene leading to the absence of the FMRP protein, i.e., a key modulator of synaptic and neuronal functionality." (PMID 36385949, 2022). "Diminished mGluR-induced dendritic localization of Sapap4 mRNA is found in the hippocampal neurons of Fmr1-KO mice, indicating a surprising coordinate regulation between Sapap4 and mGluRs that may be altered in fragile X syndrome." (PMID 36497075, 2022). "Fragile X syndrome (FXS) is a heritable developmental disorder resulting from abnormal trinucleotide CGG repeat expansion and transcriptional silencing of the X-linked FMR1 gene that encodes fragile X messenger ribonucleoprotein 1 (FMRP)." (PMID 35768828, 2022). "Among the interesting animal models of autistic-like behaviors (e.g., fmr1 knockout) there is the exploitation of fragile X syndrome (FXS) and ASD comorbidity through the expansions mutations of FMR1 gene, which greatly increase the incidence of ASD disabilities." (PMID 35721203, 2022). "Interestingly, FMR1-null mice, a rodent model of fragile X syndrome, exhibited increased ADCY1 expression and ADCY1-overexpression-like phenotype, including enhanced autism-related behaviors and increased ERK1/2 activity." (PMID 35307032, 2022). "Fmr1 is absent in the most common cause of intellectual disability and autism, fragile X syndrome (FXS)." (PMID 35434801, 2022). "Conversely, Sapap3 is decreased in both the OFC and medial prefrontal cortex (mPFC) of Fmr1-KO mice, which may contribute to the deficits in cognitive flexibility found in fragile X syndrome." (PMID 36497075, 2022). "Fragile X syndrome (FXS), the most prevalent inherited intellectual disability and one of the most common monogenic forms of autism, is caused by a loss of fragile X messenger ribonucleoprotein 1 (FMR1)." (PMID 35549943, 2022). "Finally, Drosophila is an indispensable model organism for the study of the Fragile X Messenger Ribonucleoprotein 1 (FMR1) gene triplet repeats expansion in humans, clinically known as Fragile X syndrome (FXS)." (PMID 36672829, 2022). "It is important to also note that quantitative analysis using MS-QMA was initially developed for newborn screening of fragile X syndrome in both sexes, targeting FMR1 promoter methylation, but was modified to also detect SNRPN promoter methylation in this study." (PMID 34982160, 2022). "Absence of the Fragile X Messenger Ribonucleoprotein 1 (FMRP) causes autism spectrum disorders and intellectual disability, commonly referred to as the Fragile X syndrome." (PMID 35456004, 2022).
fragile X syndrome (continued). "The silencing of the FMR1 gene occurs over 200 CGG repeats (the so-called full mutation, FM), resulting in severe diminished FMRP expression during development and in consequence the onset of the Fragile X syndrome (FXS, OMIM #300624)." (PMID 34445074, 2021). "Interestingly, these changes mirror those observed in the mouse model of Fragile X syndrome, where FMR1 knockout increased striatal DAGLα and MAGL expression." (PMID 33931678, 2021). "Therefore, evaluation over time is needed and actionability can change with new evidence for gene-disease pairs including FMR1 and fragile X syndrome." (PMID 33781310, 2021). "We assessed the concentrations of 23 trace minerals in different tissues (brain, spleen, heart and liver) of Fmr1 knockout (KO) mice that display the main phenotype of Fragile X syndrome (FXS), an intellectual disability syndrome and the best-known monogenic model of autism spectrum disorder (ASD)." (PMID 34089433, 2021). "This was suggested for the FMR1 gene, when over 200 CCG repeats cause mental retardation (Fragile-X syndrome), while the premutations of 45–200 repeats are a risk factor for Fragile-X- tremor/ataxia syndrome (FXTAS) in males and premature ovarian failure 1 (FXPOI) in females." (PMID 34440384, 2021). "In this regard, it is interesting to note that activity patterns in the Fmr1 knockout (KO) mouse, a model for the neurodevelopmental disorder fragile X syndrome, show increased correlations in the developing somatosensory and visual cortices compared to WT littermates." (PMID 33157028, 2021). "To establish a non-human primate model of the fragile X syndrome, we planned to introduce null mutations in the FMR1 gene located on the X chromosome of common marmosets." (PMID 34642413, 2021). "Moreover, women who carry a premutation-level expansion of CGG repeats in the non-coding region of the FMR1 gene (between 55 and 200 CGGs) have an increased risk of POI, as well as a high risk of having an affected child with Fragile X syndrome." (PMID 32155011, 2020). "Furthermore, in the Fmr1-knockout mouse model of fragile X syndrome, impaired eCB signaling contributes to synaptic plasticity defects that underlie impairments in episodic memory." (PMID 32471847, 2020). "On the other hand, Fmr1-KO mice are a genetically defined model for Fragile X syndrome (FXS)." (PMID 32778145, 2020). "Loss of function is excluded as patients with Fragile X syndrome, caused by FMR1 loss‐of‐function due to very long (> 200) CGG repeats, do not develop any FXTAS features." (PMID 31721251, 2020). "One such example is Fragile X syndrome (FXS), which has been linked to an expansion of the trinucleotide CGG repeat in the 5′ untranslated region (UTR) of the FMR1 gene located on the long arm of Chromosome X. When such an expansion occurs, the 5′ UTR and promoter of the gene become hypermethylated." (PMID 30846530, 2019). "Among them, most frequent is fragile X syndrome caused by the lack of family mental retardation protein (FMRP) encoded by FMR1 gene." (PMID 31561466, 2019). "Fragile X syndrome (FXS) is the most common form of inherited intellectual disability, being caused by the silencing of the fragile X mental retardation (Fmr1) gene, which encodes for the fragile X mental retardation protein (FMRP)." (PMID 31112584, 2019). "Some studies have shown that many miRNAs, such as miR-125b, miR-132, miR-101, miR-221 and miR-130b could target Fmr1 to regulate the molecular pathology of Fragile X syndrome via the synaptic structure and function or NPC fate determination." (PMID 30911036, 2019).
fragile X syndrome (continued). "Fmr1 KO is a model of Fragile X syndrome, frequently co-diagnosed with ASD." (PMID 32009915, 2019). "Fragile X syndrome (FXS) is caused by a trinucleotide repeat expansion in the 5′ promoter region of the FMR1 gene, leading to transcriptional silencing and loss of its protein product fragile X mental retardation protein (FMRP)." (PMID 30979884, 2019). "For instance, genetic analysis of FMR1 variants would not work as a screening method for Fragile X syndrome." (PMID 30665446, 2019). "Fragile X syndrome (FXS) is the leading inherited cause of neurodevelopmental disability and is characterized by a CGG trinucleotide repeat expansion in the promoter region of the fragile X mental retardation 1 gene (FMR1) on the long arm of the X chromosome." (PMID 30665413, 2019). "In addition, cytosine methylation of dCGG repeats in the FMR1 gene, which expand during progression of fragile X-mental retardation syndrome, were reported to result in stabilization of G4 structures formed by the dCGG repeats in vitro." (PMID 30736345, 2019). "Inheriting the FMR1 full mutation does not directly correspond to the development of the fragile X syndrome phenotype, but rather represents genetic risk for a particular set of cognitive, socio-emotional, and behavioral outcomes." (PMID 30642066, 2019). "For example, we recently used this neonatal virus injection approach to express GCaMP6s in barrel cortex of wild-type and Fmr1 knockout mice (a model of Fragile X Syndrome), which allowed us to record the spontaneous and whisker-evoked activity of L2/3 neurons at P14-16." (PMID 30083093, 2018). "Likewise, FMR1−/− mice, a model for the autism-related fragile X syndrome, show altered plasticity and synapse maturation in the barrel cortex." (PMID 30023428, 2018). "Similarly, from fragile X syndrome, research indicates that males with the FMR1 premutation are more likely to have ASD and ID if seizures occur in childhood." (PMID 29340132, 2018). "Deletion of FMR1 and AFF2 has been shown to cause fragile X syndrome and probably FRAXE‐syndrome." (PMID 30264515, 2018). "Behavior is used to assess memory and cognitive deficits in animals like Fmr1-null mice that model Fragile X Syndrome, but behavior is a proxy for unknown neural events that define cognitive variables like recollection." (PMID 29346381, 2018). "Group-I mGlu receptors have been the focus of extensive investigation in animal models of ID and autism since Mark Bear, Kimberly Huber, and their Associates have shown that mGlu5 receptor-dependent LTD is amplified in the hippocampus of Fmr1 knockout mice modeling Fragile-X syndrome." (PMID 29615849, 2018). "Moreover, the dynamics of spine volumes explained the greater turnover rate of spines and the smaller spine volume observed in a mouse model (Fmr1 knockout) of fragile X syndrome mental retardation than in wild-type mice." (PMID 30417082, 2018). "FRAX486 decreases hyperactivity and stereotypical movements and reduces audiogenic seizures in Fmr1 KO mice (knock out of fragile X mental retardation 1 gene: the mice show similar symptoms to Fragile X syndrome in humans, including seizures and hyperactivity)." (PMID 29596304, 2018). "However, genotype–phenotype associations across the full range of CGG repeat sizes are poorly understood because investigations of FMR1 have traditionally focused on clinical conditions of the FMR1 premutation and fragile X syndrome." (PMID 30197656, 2018).
fragile X syndrome (continued). "It should also be noted that the sample was primarily Caucasian and limited to mothers who had a child identified as having fragile X syndrome or the FMR1 premutation, which may limit generalizability." (PMID 28835209, 2017). "Fragile X syndrome (FXS) and its associated disorders are inheritable genetic diseases attributed to a trinucleotide CGG repeat expansion in the 5’ untranslated region of the fragile X mental retardation 1 (FMR1) gene." (PMID 28278294, 2017). "Research focused on women—and in particular mothers—with the FMR1 premutation is important given that the FMR1 premutation phenotype is associated with negative outcomes both for the affected individual as well as for their children with fragile X syndrome." (PMID 28469730, 2017). "The present study investigated whether racemic baclofen can remediate abnormalities of neural circuit function, sensory processing, and behavior in Fmr1 knockout mice, a rodent model of fragile X syndrome." (PMID 28451631, 2017). "Therefore, as a proof of principle for the core component of ASD—social impairment—we tested an endocannabinoid-enhancing compound on two widely studied mouse models of ASD, the BTBR and fmr1−/− (model of Fragile X Syndrome)." (PMID 28861483, 2016). "Furthermore, FMR1 mRNA silencing and loss of FMRP have been linked to hypermethylated FMR1 full mutation expansions (FM: >200 CGG triplet repeats), leading to fragile X syndrome - a common neurodevelopmental disorder found ~1 in 4000 in the general population." (PMID 27387142, 2016). "Mosaicism for FMR1 premutation (PM: 55-199 CGG)/full mutation (FM: >200 CGG) alleles or the presence of unmethylated FM (UFM) have been associated with a less severe fragile X syndrome (FXS) phenotype and fragile X associated tremor/ataxia syndrome (FXTAS)-a late onset neurodegenerative disorder." (PMID 27657133, 2016). "Fragile X syndrome, the most prevalent monogenic form of ASD, is caused by the expansion of CGG repeats upstream of the coding region in the FMR1 gene, leading to reduction of the fragile X mental retardation protein (FMRP)." (PMID 27221801, 2016). "Although we postulate a positive role for astrocyte activation on myelination in Fmr1 cerebellum, it is also possible that changes in astrocyte function could negatively contribute to the neuronal pathology characteristic of Fragile X Syndrome." (PMID 26516618, 2015). "Both p110beta level and PI3K activity are elevated and insensitive to mGluR stimulation in Fmr1 knockout neurons, suggesting that dysregulated PI3K signaling may underlie synaptic deficits in fragile X syndrome." (PMID 25767435, 2015). "Other autism-related mouse models have been shown to have interneuron subtype-specific effects including the Nlgn2 knockout mouse with impaired PV inhibitory transmission and the Fmr1 mouse model of Fragile X syndrome with impairments in both PV and SOM inhibitory networks." (PMID 26469287, 2015). "A study in cultured cerebellar granule cells from Fmr1 knockout mice suggested that memantine may exert therapeutic capacity for fragile X syndrome through a stimulatory effect on dendritic spine maturation and excitatory synapse formation." (PMID 25767435, 2015). "Fragile X syndrome, the most common inherited cause of intellectual disability, results from mutation of the FMR1 gene on the X chromosome that disrupts expression of the fragile X mental retardation protein (FMRP)." (PMID 25348928, 2014). "Fragile X syndrome is a neuro-developmental disease caused by transcriptional inactivation of the gene FMR1 (fragile X mental retardation 1) and loss of its protein product FMRP." (PMID 26740770, 2014). "Although there were clearly no samples in this set of 2,000 that were from individuals who would develop the fragile X syndrome, we examined the FMR1 CGG region in the DBS samples with FMRP lower than two SDs below the mean to see what alleles were present at the low extreme of the distribution." (PMID 25348928, 2014).